MDK (midkine)
Diseases named in the same sentence as MDK in open-access papers (continued):
Sharing a sentence is not in itself a finding about the gene and the disease.
lung adenocarcinoma (9 papers, 2013 to 2025). A carcinoma that arises from the lung and is characterized by the presence of malignant glandular epithelial cells. "iMDK inhibited the growth of MDK-expressing H441 lung adenocarcinoma cells that harbor an oncogenic KRAS mutation and H520 squamous cell lung cancer cells in vitro." (PMID 23976985, 2013). "Integrative single-cell and spatial transcriptomics analysis reveals the Midkine (MDK)–Nucleolin (NCL) pathway’s role in shaping the immunosuppressive environment of lung adenocarcinoma." (PMID 40563563, 2025). "Estradiol (E2) is reported to elevate MDK mRNA expression in lung adenocarcinoma cells LTEP-a2 and A549 in a time-dependent manner." (PMID 37240085, 2023). "A study has shown that estradiol (E2) regulates EMT in lung adenocarcinoma via transcriptional activation of MDK." (PMID 37240085, 2023). "It was found that midkine plays a pivotal role in epithelial-mesenchymal transition in lung adenocarcinoma." (PMID 26035298, 2015). "Further, no obvious systemic toxicity was observed in iMDK-treated mice, supporting the potential utility of iMDK for therapy of MDK-dependent lung adenocarcinoma." (PMID 23976985, 2013). "Collectively, these results indicate that iMDK selectively induces apoptosis in MDK-expressing H441 lung adenocarcinoma cells but not in normal NHLF cells that do not express MDK." (PMID 23976985, 2013). "However, iMDK did not reduce the cell viability of MDK-negative A549 lung adenocarcinoma cells or normal human lung fibroblast (NHLF) cells indicating its specificity." (PMID 23976985, 2013). "MDK is known to activate not only the PI3K/AKT pathway but also the MAPK pathway in primary neuronal culture and myocardium; however, in our study iMDK inhibited only the PI3K pathway but not the MAPK pathway, and actually activated the MAPK pathway in H441 lung adenocarcinoma cells." (PMID 23976985, 2013). "MDK was detected in HEK293 cells, H441 lung adenocarcinoma cells and H520 human lung squamous cell carcinoma cells but not in A549, H322 and H358 lung adenocarcinoma cells, SQ5 lung squamous cell carcinoma cells or MESO-1 malignant mesothelioma cells." (PMID 23976985, 2013). "MDK is also known to activate ERK (a MAPK) in normal non-tumorigenic cells; however, ERK and p38MAPK were not inhibited by iMDK in H441 lung adenocarcinoma cells." (PMID 23976985, 2013).
Sepsis (9 papers, 2017 to 2025). Sepsis is defined as life-threatening organ dysfunction caused by a dysregulated host response to infection. "Our previous work also found associations between plasma midkine and 28-day mortality and organ dysfunction in sepsis." (PMID 33639987, 2021). "In this study, we found that midkine was remarkedly elevated in sepsis, and was associated with increased expression of ACE and severity of lung injury both in patients and CLP models." (PMID 33639987, 2021). "Elevated MDK levels have been implicated in impaired neutrophil chemotaxis observed in sepsis." (PMID 40500394, 2025). "Plasma midkine was significantly elevated in sepsis, and was closely associated with ACE system." (PMID 33639987, 2021). "In a small study, a stimulatory effect of heparin application on serum midkine release in dialysis patients and healthy controls was determined, whereas other studies quantified midkine and inflammatory cytokine release in sepsis and vascular disease." (PMID 35211826, 2022). "In the present study, we found high circulating midkine was correlated to the severity lung injury induced by sepsis." (PMID 33639987, 2021). "We aimed to evaluate the change of midkine in sepsis and its association with angiotensin-converting enzyme (ACE) system, as well as the mechanism by which midkine induced in sepsis and lung injury." (PMID 33639987, 2021). "We subsequently studied the impact of midkine depletion in sepsis induced ALI, using a midkine RNAi adeno-associated virus (AAV) through orotracheal injection in a mouse cecal ligation puncture (CLP) model." (PMID 33639987, 2021). "Midkine, also known as neuritis growth factor 2 (NEGF2), is significantly increased in patients with severe sepsis and septic shock." (PMID 34577795, 2021). "Pulmonary midkine inhibition ameliorates sepsis induced lung injury, which might via ACE/Ang II pathway and the participation of Notch 2 in the stimulation of ACE." (PMID 33639987, 2021). "Midkine inhibition ameliorates sepsis induced lung injury, which might via ACE/Ang II pathway and the participation of Notch 2 in the stimulation of ACE." (PMID 33639987, 2021). "Targeted midkine inhibition in the lung could mitigate lung injury in CLP, implicated its detrimental role in the lung injury during sepsis." (PMID 33639987, 2021). "All these results suggested that pulmonary midkine ablation could mitigate lung injury in sepsis." (PMID 33639987, 2021). "However, the explicit role of midkine in sepsis and the mechanism by which midkine regulates ACE remains unclear." (PMID 33639987, 2021). "Studies revealed that targeted inhibition of midkine expression in the lung samples suppresses ACE activity through Notch 2 receptors and decreases the secretion of angiotensin II, thereby improving sepsis-induced ALI." (PMID 36593471, 2023). "MDK plays a role in processes such as regulation of inflammatory response, neutrophil and macrophage migration, and TLR4/NF-κB signaling activation in trauma and sepsis models." (PMID 40500394, 2025).
gallbladder cancer (8 papers, 2022 to 2025). "In ErbB pathway-mutated gallbladder cancer, upregulation of secreted midkine facilitates differentiation of immunosuppressive macrophages through biding with its receptor LRP1." (PMID 36906597, 2023). "Interestingly, a study has shown that MDK is upregulated in gall bladder cancer with ErbB pathway mutations and promotes the differentiation of immunosuppressive macrophages by interacting with LRP1 on TAM60." (PMID 40894019, 2025). "Increased MDK in tumour cells promoted immunosuppressive differentiation of tumour‐infiltrating macrophages by an interaction with its receptor LRP1 in ErbB pathway‐mutated gallbladder cancer." (PMID 35678121, 2022). "In their gallbladder cancer research, MDK interacts with its receptor LRP1, which is expressed by tumor-infiltrating macrophages, and further promotes immunosuppressive macrophage differentiation." (PMID 35558067, 2022). "Similarly, in gallbladder cancer, upregulation of MDK enhances its interaction with LRP1—expressed by tumor-infiltrating macrophages—promoting the differentiation of immunosuppressive macrophages." (PMID 41246334, 2025).
lung fibrosis (8 papers, 2017 to 2025). "The growth factor, MDK, has been implicated in the pathogenesis of hypertension, kidney disease, and lung fibrosis." (PMID 30115106, 2018). "Additionally, compared with wild‐type mice, midkine‐deficient mice showed low expression of both collagen and α‐smooth muscle actin, as well as a low value for the pathological lung fibrosis score after bleomycin administration." (PMID 28811360, 2017). "Like CCL5 and CXCL9, MDK is a profibrotic cytokine, demonstrated by its role in murine models of pulmonary fibrosis and its use as a biomarker in idiopathic pulmonary fibrosis." (PMID 39989459, 2025). "Among these genes, we found that the midkine (MDK) gene has the potential to serve as a marker of Idiopathic pulmonary fibrosis because its cellular communicating genes are differentially expressed in the epithelial cells." (PMID 38075691, 2023). "In this study, we analyzed the clinical characteristics of idiopathic pulmonary fibrosis patients in relation to midkine expression and used a mouse bleomycin‐induced pulmonary fibrosis model to investigate the role of midkine in pulmonary fibrosis." (PMID 28811360, 2017). "To determine the role of midkine in pulmonary fibrosis, we analyzed the clinical characteristics of patients with IPF and used a mouse bleomycin‐induced pulmonary fibrosis model in this study." (PMID 28811360, 2017). "In our present study conducted in the mouse bleomycin‐induced pulmonary fibrosis model, midkine expression was increased in lung tissue after bleomycin administration." (PMID 28811360, 2017). "To investigate the role of midkine in bleomycin‐induced pulmonary fibrosis, we first analyzed the time‐course of midkine mRNA expression in mouse lung tissue after intratracheal bleomycin administration." (PMID 28811360, 2017). "Further experiments using other pulmonary fibrosis models and in vitro experiments are necessary to evaluate the role of midkine on pulmonary fibrosis in detail." (PMID 28811360, 2017). "Taken together, however, the results of this study indicate that midkine is potentially involved in the development of pulmonary fibrosis by regulating inflammatory cell migration into the lung and expression of TNF‐α and TGF‐β." (PMID 28811360, 2017). "This indicates that MDK may promote lung fibrosis by interacting with Notch2 and activating angiotensin-converting enzyme (ACE) expression." (PMID 38075691, 2023). "In summary, these studies suggest that MDK plays an important regulatory role in the pathogenesis of lung fibrosis, including promoting inflammation and extracellular matrix deposition, participating in epithelial-mesenchymal transition, and modulating ACE expression." (PMID 38075691, 2023). "In the idiopathic pulmonary fibrosis patients, the serum midkine level was significantly higher than in healthy subjects, and midkine levels in the serum and bronchoalveolar lavage (BAL) fluid correlated positively with the percentage of inflammatory cells in the BAL fluid." (PMID 28811360, 2017). "Moreover, we highlight the mechanism of autophagy that the new coronavirus could try to escape in order to replicate itself, as well as on pulmonary fibrosis induced by hypoxia and on the release of cytokines and mediators of inflammation, correlating the interplay between Midkine and SARS-CoV2." (PMID 33414726, 2020). "Recent findings implicate MDK in the immunopathology of viral infections, including its upregulation during SARS-CoV-2 infection and its contribution to neutrophil infiltration and lung fibrosis via NOX1 and NOTCH2 signaling." (PMID 40500394, 2025). "Third, we could not evaluate the precise role(s) of midkine on pulmonary fibrosis in bleomycin model." (PMID 28811360, 2017).
oral squamous cell carcinoma (7 papers, 2008 to 2025). "Elevated MDK expression has also been associated with cisplatin resistance in renal and oral squamous cell carcinoma cells." (PMID 40500394, 2025). "From the literature review, MDK seems a drugable target in different cancers, including oral squamous cell carcinoma." (PMID 37743493, 2023). "The aim of this study was to evaluate serum midkine (S-MK) concentrations as a prognostic tumour marker in oral squamous cell carcinoma (OSCC)." (PMID 18682710, 2008). "In cancers such as oral squamous cell carcinoma (OSCC), MDK has been identified as a potential target for anti-angiogenic therapy." (PMID 40500394, 2025). "MDK activates the AKT pathway to promote GBM and oral squamous cell carcinoma progression." (PMID 37743493, 2023).
COVID-19 (6 papers, 2020 to 2025). A disease caused by infection with severe acute respiratory syndrome coronavirus 2. "In contrast, L–R interactions associated with the midkine (MDK) signaling pathway were observed in ciliated, secretory, and other cells in healthy, mild/moderate, and severe COVID-19 patients." (PMID 37936693, 2023). "So much so that anti-midkine monoclonal antibodies have been proposed as a new potential therapeutic strategies in COVID-19." (PMID 35308222, 2022). "In this mini review, we address the physiology of Midkine, a growth factor able to bind heparin, and its pathophysiological potential role in COVID-19 determinism." (PMID 33414726, 2020). "An increase in serum MDK levels was also reported in patients with SARS-CoV-2 infection (COVID-19)." (PMID 40943439, 2025). "Therefore, while the concept of MDR in viral diseases primarily revolves around genetic resistance, MDK’s immunomodulatory role deserves further exploration, particularly in inflammation-driven pathologies such as COVID-19." (PMID 40500394, 2025). "In this mini review, we focus the physiology of Midkine and its pathophysiological potential role in COVID-19, and we suggest to investigate Midkine as a putative biomarker of altered physiological conditions and/or a potential therapeutic target in the fight against pandemic COVID-19." (PMID 33414726, 2020). "We hypothesize that Midkine could be involved in the early stages of viral attack during COVID-19." (PMID 33414726, 2020). "In COVID-19, TNF-α has been shown to both induce and enhance MDK expression." (PMID 40500394, 2025). "We suggest the occurrence of an important interplay between Midkine, PMN, NETs, and COVID-19." (PMID 33414726, 2020). "Moreover, a crucial interplay between Midkine, neutrophils, NET, and COVID-19 might occur." (PMID 33414726, 2020).
Hypertension (6 papers, 2014 to 2023). The presence of chronic increased pressure in the systemic arterial system. "Our current study also showed AT1R was associated with advanced tumor stage, hypertension, MDK expression, and worse survival in HNSCC patients." (PMID 37743493, 2023). "Strong AT1R expression was significantly associated with AJCC tumor stage (stage IVA/B, p = 0.001), hypertension (p = 0.004), and strong MDK expression (p < 0.001)." (PMID 37743493, 2023). "MDK levels are increased in systemic hypertension and MDK interacts with ACE in the renin-angiotensin system." (PMID 25329529, 2014). "The pathophysiological roles involving midkine are diverse, ranging from AKI to progression of CKD, often accompanied by hypertension, renal ischemia and DN." (PMID 35846341, 2022).
amyloid (5 papers, 2023 to 2025). "Further proteomic profiling of these mouse models reveals the accumulated Aβ and related proteins in the brain of the 5xFAD/KO mice, supporting MDK’s protective role against amyloid pathology in AD." (PMID 38883748, 2024). "Here we present that MDK attenuates Aβ assembly and influences amyloid formation in the 5xFAD amyloidosis mouse model." (PMID 38883748, 2024). "Nevertheless, our results reveal a potential role of MDK as a resilience factor in the early stage of developing amyloid pathology, offering a promising avenue for therapeutic intervention against the disease’s progression." (PMID 38883748, 2024). "Notably, key ECM-associated proteins such as SMOC1, MDK, and SFRP1 are recurrently elevated and exhibit strong specificity to amyloid pathology, spanning both parenchymal plaques and vascular amyloid in CAA." (PMID 41282800, 2025). "Our research indicates that MDK could be one such factor, offering protective effects against Aβ-induced toxicity and contributing to resistance against amyloid pathology." (PMID 38883748, 2024).
cervical carcinoma (5 papers, 2020 to 2026). A carcinoma arising from either the exocervical squamous epithelium or the endocervical glandular epithelium. "Although there is evidence that MDK is elevated in cervical cancer, there are few studies that have conducted further research on this topic." (PMID 40429950, 2025). "In cervical cancer cells, MDK was capable of promoting metastasis, migration, and invasion via EMT in response to IFN-γ treatment via STAT1." (PMID 40429950, 2025). "The serum level of MDK was also higher in cervical cancer patients than in healthy control subjects, and it correlated with stage, tumor size, and muscle invasion, but not with para-uterine invasion, age, or vascular invasion." (PMID 40429950, 2025). "Nevertheless, some evidence exists that MDK is elevated in cervical cancers." (PMID 40429950, 2025). "Notably, MDK in cervical cancer patients with lymph node metastases was higher than in patients without lymph node metastasis, with a significant AUC and moderate sensitivity and specificity." (PMID 40429950, 2025). "When combined with squamous cell carcinoma antigen (SCCA), the current cervical cancer biomarker in use to predict lymph node metastasis and prognosis, the combination of SCCA and MDK had a higher AUC than either alone, indicating higher diagnostic accuracy." (PMID 40429950, 2025). "In conclusion, the MDK-NCL signaling network may influence cervical cancer by impacting the immune microenvironment and promoting the malignant phenotype of tumor cells, with NCL expression linked to immune suppression, while MDK remains a potential target for cervical cancer therapy." (PMID 40777026, 2025). "The top molecule signalling between the neoplastic region (cluster 8) and the adjacent cluster 9 was midkine (MDK), a well‐recognised gene overexpressed by various human malignancies, including cervical cancer, and playing a role in cell growth, survival metastasis, migration, and angiogenesis." (PMID 41362277, 2026). "The expression of MDK mRNA and proteins have been found to be elevated in cervical cancer tissues relative to non-cancerous cervical tissues, with protein expression also correlating with tumor size and stage." (PMID 40429950, 2025). "Trop2 also exhibits tumor suppressive functions in cervical cancer cells, where it similarly inhibits the activation of IGF-1R and anaplastic lymphoma kinase (ALK), possibly through binding to their ligands IGF-1 and midkine (MDK)." (PMID 33187148, 2020).
heart failure (5 papers, 2017 to 2025). Inability of the heart to pump blood at an adequate rate to meet tissue metabolic requirements. "As organisms age, expression of MDK diminishes; however, in adults, MDK expression is associated with acute and chronic pathologic conditions such as myocardial infarction and heart failure (HF)." (PMID 28920060, 2017). "Furthermore, the pro-inflammatory cytokine midkine (MK) has been investigated as a biomarker in heart failure." (PMID 40002917, 2025). "The circulating level of MDK was increased in patients with heart failure, and MDK may be a potential marker of heart failure with DCM." (PMID 38310240, 2024). "It will be of interest whether midkine is similarly regulated in patients with cardiac failure and/or vascular diseases undergoing a stress test, even in the absence of kidney malfunction." (PMID 35211826, 2022). "Recombinant human midkine is available and enters clinical studies, e.g., to combat heart failure." (PMID 35211826, 2022). "FLNA, ITGA6, ITGA1, and MDK may play an important role in neurons in heart failure with DCM." (PMID 38310240, 2024). "Here, we demonstrated that serum midkine levels in patients with PAH are considerably higher than in the patients with heart failure without pulmonary arterial remodeling." (PMID 32587339, 2020). "Serum midkine levels were significantly increased in patients with PAH in comparison with those with heart failure without increased PVR." (PMID 32587339, 2020).
lymph node metastasis (5 papers, 2012 to 2025). "Midkine has been proposed as a serum biomarker for high-risk EC patients, and preoperative serum levels have been shown to correlate with lymph node metastasis." (PMID 30519148, 2018). "This is consistent with the finding that Patient 1#, who had high MDK expression in tumor tissue and exhibited lymph node metastasis." (PMID 39540244, 2025). "A limited number of researches identified independent risk factors for the early recurrence of cHCC as follows: tumor size, tumor number, MiVI, MaVI, SN, lymph node metastasis, Midkine, DCP, CA19–9, and poor differentiation." (PMID 35227269, 2022).